G6PD (glucose-6-phosphate dehydrogenase)
Diseases named in the same sentence as G6PD in open-access papers (continued):
Sharing a sentence is not in itself a finding about the gene and the disease.
tumor (continued). "Inhibition of glucose-6-phosphate dehydrogenase activity could reduce cellular NADPH production, thereby increasing oxidative stress and limiting tumor progression." (PMID 39796677, 2024). "G6PD is a very important biomarker in the pentose phosphate pathway (PPP), which is a precursor for nicotinamide adenine dinucleotide phosphate (NADPH) production in tumor cells." (PMID 38297250, 2024). "High expression of G6PD produces high levels of NADPH via the PPP pathway, as well as an increase in glutathione, which in turn counteracts oxidative stress and DNA damage, which promotes immune escape, tumor progression, and drug resistance." (PMID 38297250, 2024). "However, the staining intensity of the signature proteins—PML, G6PD, SLC7A11, and STMN1—in the tumor tissues was notably stronger than that in the paired adjacent tissues." (PMID 38317842, 2024). "A recent study has shown that a lack of BHMT can lead to hepatocarcinogenesis and tumor growth by increasing the activity of glucose-6-phosphate dehydrogenase (G6PD) and pentose phosphate pathway (PPP) metabolism in HCC." (PMID 39516467, 2024). "Studies have shown that PIKE-A activation of Akt binds to STAT3, stimulating FYN and inducing STAT3 phosphorylation, thereby enhancing G6PD transcription, activating PPP metabolism, promoting DNA and NADPH synthesis, and inhibiting ROS production, ultimately fostering tumor growth." (PMID 39624082, 2024). "Moreover, their results suggest that JAK2-dependent G6PD phosphorylation is essential for IL-6-induced nucleotide synthesis and thus plays a crucial role in OSCC cell proliferation and tumor growth." (PMID 39796677, 2024). "Given the significant impact of BCKDK on tumour proliferation, we hypothesised that BCKDK plays a proliferative role through G6PD." (PMID 39025830, 2024). "We hypothesized that G6PD depletion would suppress NADPH production in KL lung tumors, disrupting redox homeostasis and leading to cell death in the stressed tumor microenvironment." (PMID 38997257, 2024). "G6PD is crucial for NADPH generation, and down-regulation of G6PD may enhance tumor sensitivity to chemotherapeutic drugs." (PMID 37958751, 2023). "Our previous findings demonstrated that positive regulation of G6PD transcriptional activity by various transcription factors (including YY1, NeuroD1, PBX3, and p52-ZER6) enhances tumor cell proliferation by promoting tumor cell nucleotides and lipid biosynthesis." (PMID 38139067, 2023). "We also found that G6PD, NRAS and HRAS may have a positively moderate correlation with most of IGCs in Tumor cell/APC/DC group than in T cell group." (PMID 37143953, 2023). "As an enzyme that catalyzes the first step of PPP, increased G6PD expression and enzymatic activity lead to enhanced PPP flux, thereby providing energy and precursors for macromolecule biosynthesis and subsequently driving tumor progression 50-54." (PMID 37781025, 2023). "Nevertheless, the potential of G6PD as a target for anti-tumor therapy should not be underestimated, especially when used in combination with other anti-tumor drugs." (PMID 38139067, 2023). "While this and a previous study show that p71-ZER6 could enhance tumor cell proliferation and colony formation, it is likely that p71-ZER6 is involved in tumorigenesis through a pathway other than G6PD/PPP." (PMID 36977688, 2023). "G6PD has been suggested as a potential therapeutic target in HCC, as inhibiting its activity could help prevent tumor progression." (PMID 37627157, 2023). "The prognostic value, tumor immunity, and biological significance of G6PD have not been well understood." (PMID 37601657, 2023).
tumor (continued). "Our previous study also revealed that NeuroD1 could promote tumor cell metabolic reprogramming, as it could enhance the pentose phosphate pathway (PPP) by promoting the transcription of the PPP rate-limiting enzyme G6PD." (PMID 38134213, 2023). "Targeting G6PD and other metabolic regulators, such as pyruvate kinase isozymes M1/M2 (PKM1/2), monocarboxylate transporter (MCT), and isocitrate dehydrogenase 1/2 (IDH1/2), has attracted attention as a potential anti-tumor therapeutic strategy." (PMID 38139067, 2023). "Importantly, in clinical samples, we verified that G6PD and SERPINE1 were expressed higher in the tumor tissues of HCC patients than in control samples." (PMID 37993470, 2023). "The expression levels of G6PD, Cyclin E1 and MMP9 protein were significantly increased in ACHN-G6PDOE-derived tumor tissues, whereas they were obviously decreased in Caki-1-G6PDSi-derived tumor tissues compared with the corresponding controls." (PMID 34975298, 2022). "G6PD is the rate-limiting enzyme within the PPP, a pathway that serves as the main source of reducing equivalents (NADPH) and pentose phosphate needed for tumor cell activities." (PMID 36059624, 2022). "Secondly, the TCGA transcriptional expression analyses of G6PD and MMP9 were test results of human ccRCC tumor specimens and normal control kidney tissues, which were different from the detection of mRNA and protein expression levels based on stably transfected cell models." (PMID 34975298, 2022). "Furthermore, glucose 6-phosphate dehydrogenase (G6PD) produces ribose and NADPH in the tumor cells through the pentose phosphate pathway (PPP) as a source of energy for tumor growth." (PMID 36588730, 2022). "G6PD as a crucial rate-limiting enzyme of PPP, greatly facilitates tumor invasion." (PMID 34235156, 2021). "Furthermore, the in vivo study revealed that knockdown of NRF2 markedly decreased the protein levels and enzymatic activities of G6PD and TKT in the excised tumors from Ca9-22-D1 xenograft tumor-bearing mice." (PMID 33859744, 2021). "Furthermore, the K171ac of G6PD regulated by TSP50 is required for TSP50‐induced cell proliferation in vitro and tumour formation in vivo." (PMID 33630390, 2021). "Finally, the role of G6PD K171 acetylation regulated by TSP50 in cell proliferation and tumour formation was investigated." (PMID 33630390, 2021). "Interestingly, the expression of glucose-6-phosphate dehydrogenase (G6PD), the rate limiting enzyme of the oxidative branch of the PPP, was upregulated in fructose A52 tumours, while downregulated in the Huh7 fructose group." (PMID 33028928, 2020). "The critical importance of G6PD and the PPP in supporting cell proliferation has been confirmed in several studies demonstrating that its inhibition leads to a significant reduction in tumor and plasmodium cell proliferation." (PMID 31737625, 2019). "Differences in the pentose phosphate pathway were less clear; while expression of G6PD was upregulated in HPV−ve tumours, other pentose pathway genes were not differentially expressed." (PMID 30655616, 2019). "However, in PFKL- or G6PD-overexpressing cells, knocking down TA73 had a minimal effect on tumor growth." (PMID 30409970, 2018). "Notably, G6PD activity and expression are elevated by oncogenes such as K-RAS12, suppressed by tumor suppressors like P5313 or PTEN14, and correlate with poor survival in the context of ID1 expression." (PMID 29904144, 2018). "Further in vivo xenograft experiments revealed that stable overexpression of WT G6PD or T466D mutant, but not that of T406A, T406D, or T466A, in endogenous G6PD-knockdown HeLa cells promoted tumor growth." (PMID 29138396, 2017).
tumor (continued). "In vivo experiments further shows that silencing G6PD with lentivirus or non-viral gene delivery vector enhances oxaliplatin anti-tumor effects in cell based xenografts and PDX models." (PMID 28692052, 2017). "Altogether, both G6PD and TKT are crucial enzymes in modulating the tumor metabolic phenotype." (PMID 29290982, 2017). "This conclusion is not totally the same as our previous statistical analyses of The Cancer Genome Atlas (TCGA) datasets, but provides sufficient information for further unravelling the correlation between G6PD overexpression and RCC tumor initiation and progression." (PMID 29312589, 2017). "Similar results were observed in xenograft experiments using Hep3B cells, in which restoring the expression of WT G6PD, but not its 406A and 466A mutants, in G6PD knocking down cells promoted tumor growth." (PMID 29138396, 2017). "When these candidates were tested for their effect on ongoing tumor proliferation in explants, we were surprised to find that neither G6PD nor JNK depletion were able to effectively inhibit brat tumor growth." (PMID 28912546, 2017). "Here the authors generate mice that modestly overexpress G6PD and report increased lifespan in females, and no negative effects on tumour formation in various genetic models." (PMID 26976705, 2016). "Immunostaining and western blot affirmed an elevation of G6PD protein level in the same samples while the tumor samples showed a higher G6PD than that in the non-tumor samples." (PMID 26583321, 2015). "According to the Kaplan-Meier analysis, mean PFS time of patients with G6PD-negative and G6PD-positive expression tumor were 71.36 ± 6.53 and 32.25 ± 5.67 months, respectively (P = 0.002)." (PMID 26607846, 2015). "According to the Kaplan-Meier analysis, the mean PFS times of patients with G6PD-negative and G6PD-positive expression tumor were 71.36 ± 6.53 and 32.25 ± 5.67 months, respectively (log-rank test, P = 0.002)." (PMID 26607846, 2015). "We have analyzed the sequence heterogeneity of the transcripts of the human HPRT and G6PD single copy genes that are not considered tumor markers." (PMID 20186333, 2010). "This suggests that single agent inhibition of G6PD may not be as efficacious for both tumor genotypes." (PMID 40802750, 2025). "Additionally, OB EVs caused metabolic changes, including reduced lactate levels and decreased pyruvate kinase (PK) activity, while increasing glucose-6-phosphate dehydrogenase (G6PDH) activity, suggesting metabolic reprogramming that supports tumor cell survival and proliferation." (PMID 40485730, 2025). "Notably, G6PD and IDH2—key enzymes in the pentose phosphate pathway and TCA cycle respectively—may protect tumor cells from radiation-induced oxidative damage through enhanced NADPH production and antioxidant capacity." (PMID 41306526, 2025). "Second, deeper molecular investigations are required to elucidate the specific regulatory mechanisms of G6PD on HIF-1α, alongside comprehensive spatial single-cell analyses and in vivo lineage tracing to resolve spatial heterogeneity in G6PD-HIF-1α interactions within tumor microenvironments." (PMID 41050691, 2025). "Finally, to confirm if protein levels of genes that were differentially expressed between mouse diet groups and/or tumours were similarly altered, Western blots of mouse non-tumour and tumour tissues were analysed for expression of G6PD, ASCL4 and SREBP1." (PMID 39203941, 2024).
tumor (continued). "Subcutaneous transplantation of these cells into BALB/c-nu/nu mice revealed that p52-ZER6 silencing decreased the volume of the tumors formed, whereas G6PD overexpression largely restored it, suggesting that knocking down p52-ZER6 could slowdown tumor growth, most plausibly by suppressing the PPP." (PMID 36977688, 2023). "Moreover, its structural homolog, the TAP73 gene, not only activates G6PD and promotes the biosynthesis of PPP but also up-regulates the expression of PFKL via transcription, thus enhancing the Warburg effect and accelerating the proliferation of tumor cells." (PMID 38139250, 2023). "Increased activity of G6PD/PPP, which is frequently observed in various tumors, enhances the production of NADPH, which might decrease tumor cell drug sensitivity towards DNA-damage-based anti-tumor drugs such as oxaliplatin, doxorubicin, and daunorubicin." (PMID 38139067, 2023). "During tumor growth, reprogrammed glucose metabolism is involved to meet the demand of glycolytic intermediates for macromolecule biosynthesis, during which the NSD2 has been reported to play a role by regulating key glucose metabolism regulators, such as TIGAR, HK2, and G6PD." (PMID 35354439, 2022). "Several key proteins involved in glycometabolism, such as glucose 6 phosphate dehydrogenase (G6PD), glucose transporter-1 (GLUT-1), demonstrate a higher expression level in BC cells, and their expressions have been reported to positively correlate with the tumor stage." (PMID 35928440, 2022). "Therefore, increased use of the PPP would decrease glycolytic activity and so the lack of a substantial effect of G6PD silencing on the primary tumour growth." (PMID 34932167, 2021). "However, the inhibition of tumor growth was not as dramatic as that mediated by G6PD silencing in our previous study, which most probably due to low drug bioavailability." (PMID 33041664, 2020). "In addition to G6PD and other enzymes in the oxidative branch of the PPP, enzymes within the nonoxidative branch have also been suggested to be important sources for ribosome 5‐phosphate production in tumor cells." (PMID 32997407, 2020). "Moreover, DHEA inhibits tumor development and progression in many types of animal models, although the clinical effectiveness of DHEA alone is limited because of a relatively high IC50 level to control G6PD activity and subsequent high oral doses." (PMID 32487689, 2020). "Hence, G6PD activity might determine a dynamic balance between cell proliferation versus resilience under stress conditions, and the effect of PPP inhibition needs to be evaluated in a tumor‐specific context." (PMID 38115544, 2024). "Furthermore, it remains to be determined whether G6PD might also influence tumor development in ways that are not directly related to its known metabolic and enzymatic functions." (PMID 38139067, 2023). "Therefore, G6PD-mediated activation of PPP may promote tumor and non-neoplastic disease progression." (PMID 36091812, 2022). "Importantly, although less significant than its effect on G6PD, p52-ZER6 might also affect the expression of other glucose metabolism-related genes, such as FH, PKM2, TIGAR, LDHA, GLUT1, and HK2, thereby contributing to tumor metabolic reprogramming through multiple pathways." (PMID 36977688, 2023). "Even though the knockdown of the G6PD gene does not affect the amount of NADPH, which is important for tumor development, the knockdown of this gene alone results in inhibition of tumor growth." (PMID 35301361, 2022).
tumor (continued). "The largest number of changes in gene expression (n = 8) between tumour and non-malignant groups were identified in metabolic genes (PFKL, ATP5A1, UQCRFS1, CPT2, COX5A, ACLY, GPD2, and G6PD)." (PMID 36142793, 2022). "To investigate the role of PFKL and G6PD in tumor growth in vivo, we injected control, PFKL-overexpressing, and G6PD-overexpressing HCT116 cells, each with and without TAp73-knockdown, into immune compromised mice." (PMID 30409970, 2018). "We think this unlikely, as other similar interventions, such as PEPCK-RNAi never acquired resistance and for G6PD or JNK we did not see a period of limited growth followed by rapid expansion, which would be expected if tumours were acquiring resistance." (PMID 28912546, 2017). "Moreover, upon G6PD or PFKL overexpression in HCT116 cells, knockdown of TAp73 no longer impairs tumor growth in xenograft mouse models." (PMID 30409970, 2018).